RETN (resistin)
Diseases named in the same sentence as RETN in open-access papers (continued):
Sharing a sentence is not in itself a finding about the gene and the disease.
Insulin resistance (continued). "Indeed, we have previously shown that adiponectin and FGF21 signaling pathways are completely abolished by resistin central treatment leading to hypothalamus inflammation and to overall insulin resistance." (PMID 36078135, 2022). "This reduction of adipogenesis by Sirt3 inhibitor was associated with increased proinflammatory cytokines including IL6, resistin, and TNF, suggesting Sirt3 downregulation might increase the risk of insulin resistance and metabolic abnormalities." (PMID 35409099, 2022). "Notably, the adipose tissue plays a key role in inflammation-induced insulin resistance as a massive source of inflammatory cytokines and specific adipokines, including leptin, resistin and adiponectin." (PMID 35327570, 2022). "Indeed, P. gingivalis LPS exposure leads to increased secretion of resistin and leptin involved in insulin resistance and decreased secretion of adiponectin recognized as an insulin-sensitizing molecule." (PMID 35327570, 2022). "Moreover, VDD would result in insulin resistance, up-regulation of hepatic inflammatory and oxidative stress genes, and higher hepatic resistin gene expression." (PMID 36172527, 2022). "Insulin resistance is a hallmark of the metabolic syndrome associated with obesity, TNF-α, IL-6, adiponectin, resistin, and free fatty acids, all of which are contained in visceral fat, may have a role in the development of insulin resistance." (PMID 35159388, 2022). "Moreover, the level of circulating resistin, an adipokine promoting insulin resistance, was significantly higher in HF+MA-fed mice compared with HF controls." (PMID 35740864, 2022). "Furthermore, IL-6 and TNF-α enhance the survival of inflammatory factors such as resistin, reinforcing insulin resistance." (PMID 36355818, 2022). "The pro-inflammatory cytokines are known to play a key role in the pathogenesis of diabetes where resistin may be responsible for these inflammatory processes and insulin resistance." (PMID 36612600, 2022). "However, a recent meta-analysis found that resistin levels are correlated with insulin resistance in obese and type 2 diabetes mellitus patients." (PMID 34202323, 2021). "In addition, TNF-α increases circulating levels of leptin and resistin when interacting synergistically with IL-6, favoring increased peripheral insulin resistance and greater chances of developing T2DM." (PMID 33520042, 2021). "In addition, it increases the secretion of leptin, resistin, and inhibitor-1 of plasminogen activation, which promotes insulin resistance." (PMID 34568974, 2021). "Beside, resistin, an adipokine, also promotes inflammation and insulin resistance via TLR4." (PMID 33686181, 2021). "Moreover, delayed intervention with ASEC, PRO, or ASEC + PRO reversed HFD-induced impaired glucose tolerance, insulin resistance, and elevated serum leptin and resistin levels." (PMID 34579036, 2021). "In addition, previous studies have demonstrated that resistin, PAI-I, and adiponectin are associated with insulin resistance/sensitivity." (PMID 33705641, 2021). "In addition to its role in energy storage and metabolic balance, adipose tissue is an active endocrine organ releasing several factors involved in systemic inflammation, insulin-resistance and CVD risk, including resistin." (PMID 34496965, 2021). "RETN could induce insulin resistance by inhibiting the phosphorylation of IRS, Akt and ERK 1/2 proteins." (PMID 34952629, 2021). "Both adiponectin and resistin participate in the mechanism of insulin resistance." (PMID 35056501, 2021). "Previous studies of resistin mainly focused on its inflammatory and insulin resistance effects." (PMID 34659568, 2021). "In these cells, BPA is capable of reducing adiponectin production and secretion and induce resistin expression, a condition that generally characterizes obese subjects, where adiponectin levels are usually reduced and resistin levels are elevated, determining insulin resistance." (PMID 34829943, 2021).
Insulin resistance (continued). "Higher levels of follistatin and resistin are associated with the lack of pre-ovular follicle development in PCOS or insulin resistance." (PMID 33740002, 2021). "The name “resistin” was established based on its action of increasing insulin resistance." (PMID 34202323, 2021). ", In our study, resistin levels correlated with the degree of insulin resistance, as assessed by HOMAIR, and with all the components of the metabolic syndrome (waist circumference, hypertension, HDL-C/TG levels), although the association remained significant only for TG at multivariate analysis." (PMID 34496965, 2021). "Experiments on animals have shown that resistin is involved in inducing insulin resistance." (PMID 34947881, 2021). "On the other hand, resistin belongs to molecules that impair insulin-stimulated glucose uptake, which may lead to insulin resistance." (PMID 35056501, 2021). "However, “In type 2 diabetes mellitus and obese individuals, resistin levels are positively correlated with insulin resistance in people with hyperresistinemia”." (PMID 35011183, 2021). "High levels of leptin and resistin occurring in obese individuals, lead to the emergence of insulin resistance, whereas adiponectin may prevent it." (PMID 34684622, 2021). "In the brain, palmitic acid and resistin trigger neuroinflammation and insulin resistance, but their link at the neuronal level is unknown." (PMID 33686181, 2021). "Combined exenatide and metformin showed better effects on female than male patients for improving insulin sensitivity and serum lipid profile, reducing insulin resistance, increasing adiponectin levels, and decreasing the levels of HbA1c, BMI, resistin, TNF-alpha, CRP (p<0.05)." (PMID 34367059, 2021). "In addition, resistin, a “bad” adipocytokine involved in inflammatory and/or insulin resistance, also tends to be lower in mice fed BSCP." (PMID 33924369, 2021). "Thus, the potential role of resistin in stress-induced peripheral insulin resistance during injury shows promise and should be the subject of further study." (PMID 33097799, 2020). "Therefore, resistin has pro-inflammatory properties and its higher levels indicate the development of insulin resistance, diabetes, obesity, and cardiovascular disease." (PMID 32560148, 2020). "In rodents, the main role of resistin is its involvement in inducing insulin resistance." (PMID 32375231, 2020). "Moreover, some authors suggested that resistin is not only a pro-inflammatory indicator, but also an energy deficit signaler, and is related to insulin resistance." (PMID 32560148, 2020). "Resistin is secreted by WAT and macrophages and has an important role in inflammatory processes that trigger insulin resistance, with some studies having determined that elevated plasma levels of resistin are a predictor of the future development of type 2 diabetes mellitus." (PMID 33227979, 2020). "Even though experimental findings suggest that resistin might be involved in the diabetes pathophysiology and glucose homeostasis, its role in the development of insulin resistance and GDM in pregnancy remains unclear." (PMID 33321877, 2020). "Glucose dysmetabolism, insulin resistance, and changes in adipokines secretion (resistin in particular) may be involved in the development and progression of breast cancer in overweight/obese pre- and postmenopausal women." (PMID 32903534, 2020). "Furthermore, our data demonstrate for the first time that resistin release requires lipolysis, and the lipolysis-dependent induction in our study strongly correlated with insulin resistance and impaired glucose disposal." (PMID 33097799, 2020). "Previous studies have shown that EFT is closely related to insulin levels in serum in addition to Resistin mRNA levels and may be involved in the formation of insulin resistance." (PMID 30630489, 2019).
Insulin resistance (continued). "Another suggested mechanism is that central resistin might induce hypothalamic insulin resistance through the impairment of adiponectin and FGF21 signaling known as insulin-sensitizing hormones." (PMID 30906281, 2019). "The present study was designed to clarify the correlation between resistin and insulin resistance." (PMID 31803062, 2019). "In this context, data from a ‘humanized mouse’ model in which only human resistin was produced by macrophages suggested that human resistin might display pro-inflammatory characteristics mediating insulin resistance." (PMID 31569348, 2019). "Although there are exceptions, resistin is thought to induce insulin resistance in mice." (PMID 31208019, 2019). "Interestingly, intracerebroventricular (ICV) resistin treatment induces overall inflammation and insulin resistance through the activation of hypothalamic TLR4 signaling pathway." (PMID 30845245, 2019). "Meta-regression of correlations between insulin resistance and resistin." (PMID 31803062, 2019). "Rodent studies showed a clear role of resistin in the development of insulin resistance." (PMID 31803062, 2019). "Notably, the levels of these three major adipokines—leptin, resistin, and adiponectin—were shown to correlate with insulin resistance." (PMID 31540528, 2019). "In our study, the concentration of circulating resistin in diabetic animals was lower compared with the control, which suggests that this hormone is not implicated in the development of insulin resistance in GK rats." (PMID 31623226, 2019). "Resistin may be an important adipokine linking central adiposity and insulin resistance in South Asian women." (PMID 30778042, 2019). "Nevertheless, the relationship between resistin and insulin resistance in humans is under debate." (PMID 31803062, 2019). "Adipose tissue does not only contribute to NAFLD as a source of FA; adipocytes secrete adipokines that have protective effects against NAFLD, such as adiponectin and visfatin, as well as resistin and leptin, which contribute to hepatic steatosis and insulin resistance." (PMID 31771244, 2019). "Serum and adipose tissue resistin may be an important adipocytokine linking central adiposity, insulin resistance and dysglycemia in these women." (PMID 30778042, 2019). "Higher levels of resistin are found in a condition of insulin resistance." (PMID 31195622, 2019). "The general consensus is that resistin in metabolism plays a pathologic role in promoting insulin resistance, atherosclerosis, and hypertension, whether in mouse or human studies." (PMID 30809105, 2019). "All together, these data clearly reveal resistin/TLR4 as a new regulatory pathway of neuronal autophagy, and suggest that resistin-dependent neuronal autophagy could be a key contributor of hypothalamic inflammation and insulin resistance." (PMID 30906281, 2019). "There are also several other hypotheses regarding the controversial correlation between resistin and insulin resistance." (PMID 31803062, 2019). "This might be explained by the hypothesis that resistin might be the principal factor which induced insulin resistance at high levels." (PMID 31803062, 2019). "That study indicated that resistin might be a therapy targeting insulin resistance in the patients with hyperresistinemia." (PMID 31803062, 2019). "Subgroup analyses of correlations between insulin resistance and resistin." (PMID 31803062, 2019). "Nevertheless, it is accepted that resistin is generally involved in inflammation and insulin resistance, and subsequently in the development of different pathologies such as coronary artery disease, atherosclerosis, type 2 diabetes, psoriasis and colorectal cancer." (PMID 31443349, 2019). "Thus, we conclude that maternal resistin led to a slight glucose intolerance, but when combined to the hyperinsulinemia found in CR group this fairly reveals most likely a potential insulin resistance." (PMID 30845245, 2019).
Insulin resistance (continued). "It has been shown that six-day resistin treatment elevated plasma glucose and insulin levels, as well as HOMA-IR in wild-type mice, confirming that resistin may induce insulin resistance." (PMID 31013835, 2019). "Because klotho is reportedly associated with insulin resistance, the association between FGF23 and resistin could potentially result from the effects of klotho." (PMID 30228288, 2018). "Furthermore, ROC curve analyses demonstrate the diagnostic potential of resistin/RBP4 and MCP-1/RBP4 indexes for T2DM and β-cell function while leptin/MCP-1 index is an additional indicator for insulin resistance/sensitivity." (PMID 29785210, 2018). "Subsequent experimental studies showed that resistin may be a mediator of insulin resistance, likely via a decrease in the phosphorylation of 5′ adenosine monophosphate-activated protein kinase (AMPK) in the liver." (PMID 29848323, 2018). "Therefore, and to analyze the influence of central s-resistin on the development of insulin resistance with ageing, we decided to knockdown central s-resistin levels in 24-months-old Wistar rats." (PMID 29500410, 2018). "Therefore, in the presence of increased adiposity and insulin resistance, certain adipokines are affected, including adiponectin, leptin, and resistin." (PMID 29601521, 2018). "Conversely, resistin inhibits insulin signals, inducing insulin resistance." (PMID 30294680, 2018). "Further studies showed that in humans, resistin is mainly produced by leukocytes, especially macrophages, and its contribution to the development of insulin resistance remains unclear." (PMID 30517161, 2018). "Resistin is a lesser known adipokine that has been observed to promote insulin resistance." (PMID 29601521, 2018). "In addition, a previous study has proposed a novel index based on the relative proportion of adiponectin-to-resistin to predict insulin resistance." (PMID 29785210, 2018). "However, at present few studies have investigated the functional role of resistin in the development of insulin resistance in human skeletal muscle cells." (PMID 29760587, 2018). "Leptin and resistin are also related to obesity, insulin resistance, and inflammation." (PMID 30400222, 2018). "Resistin is an important adipokine that contributes to insulin resistance in mice." (PMID 30416448, 2018). "IRS1 expression levels in hepatocytes have been reported to be modulated also by miR-145; such miRNA was found upregulated in liver of mice treated with resistin, thus being involved in resistin-induced insulin resistance through IRS1 expression levels reduction." (PMID 30469501, 2018). "In addition, we also examined the diagnostic potential of resistin/MCP-1, resistin/RBP4, visfatin/MCP-1, visfatin/SFRP5 and MCP-1/RBP4 indexes in insulin resistance/sensitivity and β-cell function." (PMID 29785210, 2018). "Based on these data we hypothesized that s-resistin could have an important role in the hypothalamic function and in the development of central and peripheral insulin resistance." (PMID 29500410, 2018). "RETN and HSP72 are adipocyte factors associated with insulin resistance." (PMID 30154394, 2018). "We speculate that resistin may enhance the release and activation of leukocytes, and that this is probably the main source of resistin at the site of inflammation which then contributes to the development and progression of insulin resistance and MetS." (PMID 29075331, 2017). "This may add to insulin resistance, which has been recently identified in resistin-incubated HepG2 cells." (PMID 28661458, 2017). "The role of resistin in insulin resistance of PCOS is still controversial." (PMID 27473078, 2017). "RELMβ, a secretory protein homologous to resistin, increases insulin resistance." (PMID 29262630, 2017).
Insulin resistance (continued). "Among RA-related risk factors, proinflammatory cytokines (TNF-α, IL-6), oxidative stress, an increase of leptin and resistin (proatherogenic hormones) and the decrease of adiponectin (antiatherogenic hormone), and insulin resistance play the most important role in accelerated atherogenesis." (PMID 29200598, 2017). "Leptin, adiponectin, and resistin are peptide hormones, which might have a potential role in the mechanism leading to insulin resistance." (PMID 27212946, 2016). "Hyperthyroid patients presented with significantly lower serum levels of high-density lipoprotein cholesterol, LDLC and leptin, as well as higher levels of fasting insulin, resistin, adiponectin and homeostasis model insulin resistance index (HOMA-IR) than control (p < 0.05)." (PMID 27193069, 2016). "Besides its contribution to the insulin resistance, it has been shown that resistin can trigger a proinflammatory state by regulating various biological processes, thus contributing to inflammatory diseases." (PMID 28097156, 2016). "Adiponectin increases insulin sensitivity, while resistin increases insulin resistance." (PMID 27651836, 2016). "Adiponectin increases insulin sensitivity, whereas resistin increases insulin resistance." (PMID 27651836, 2016). "Increased resistin may lead to a chronic subinflammatory state that plays a central role in the development of insulin resistance, type 2 diabetes and cardiovascular diseases." (PMID 27193069, 2016). "After adjustment for age, waist circumference, resistin, CRP, PAI-1, adiponectin and glycated hemoglobin levels, the association of having insulin resistance and higher levels of IL-6 (OR = 1.390, p = 0.005) and MCP-1 (OR = 1.006, p = 0.026) became stronger (model 4)." (PMID 26862350, 2016). "Moreover, this study demonstrated that the ratio of resistin to adiponectin was more strongly correlated with insulin resistance indexes and key metabolic endpoints of T2D and MS than adiponectin and resistin levels alone." (PMID 27536890, 2016). "Markers of microbial fermentation of FOPS, including total SCFA, acetate, and cecal weight were negatively correlated with many host metabolic markers, including body weight gain, fasting glucose, fasting insulin, index of insulin resistance, C-peptide, adipose tissue weights, resistin, and leptin." (PMID 26731528, 2016). "So authors suggested that resistin might be involved in the insulin resistance state that connected with thyrotoxicosis." (PMID 27637079, 2016). "Cytokines, and specially resistin, may be some of the factors modulating insulin resistance in T1D and therefore warrant additional studies." (PMID 26273680, 2015). "However, the exact role of resistin in the pathogenesis of insulin resistance and T2D in humans is still unclear." (PMID 25945322, 2015). "Additionally, our analysis supports the relationship between resistin level and insulin resistance, even though this correlation was borderline and studied only in PAI cohort." (PMID 25129652, 2015). "While high resistin levels are associated with rheumatoid arthritis, coronary heart disease and insulin resistance, a low resistin plasma level may be correlated with a high hospitalization rate in dialysis patients." (PMID 26425347, 2015). "The increased level of resistin level and its correlation to other inflammatory cytokines may be related to the increased fat mass and could be involved in the development of insulin resistance observed in our patients." (PMID 26273680, 2015). "The relationship between resistin and insulin resistance has been controversial." (PMID 25904939, 2015). "In addition, mouse resistin has been shown to promote insulin resistance by increasing hepatic gluconeogenesis." (PMID 26097512, 2015). "Indeed, in an inflammatory environment promoted by LPS stimulation, human resistin was upregulated and contributed to inflammation and insulin resistance." (PMID 25568944, 2015).